MIF (macrophage migration inhibitory factor)
Diseases named in the same sentence as MIF in open-access papers (continued):
Sharing a sentence is not in itself a finding about the gene and the disease.
brain injury (3 papers, 2020 to 2023). Acute and chronic (see also brain INJURIES, CHRONIC) injuries to the brain, including the cerebral hemispheres, CEREBELLUM, and brain STEM. "Increased serum MIF concentrations have a close relationship to inflammation, trauma severity, and clinical outcomes, substantiating MIF as a good prognostic biomarker after traumatic brain injury." (PMID 32964038, 2020). "In contrast to the time-course of changes in serum, MD MIF levels peaked during EPd1−4 and progressively decreased during the first 2 weeks after hemorrhage, which is reminiscent of the stereotyped response of various brain cytokines to injury observed after aSAH and traumatic brain injury." (PMID 36712451, 2022). "This study found that patient concentrations were significantly higher than controls and that serum MIF concentrations were highly correlated with CCS, suggesting that elevated serum MIF may be a valid biomarker for early detection of CCS after traumatic brain injury." (PMID 37538256, 2023).
colon adenocarcinoma (3 papers, 2017 to 2025). "As a result, NF‐1 treatment can convert “cold” tumors into “hot” tumors by reshaping the MIF‐mediated immunosuppressive network, NF‐1 treatment thus enabling effective immunotherapy in BRCA and enhancing the ICB efficacy in colon adenocarcinoma (COAD)." (PMID 39908165, 2025). "The Macrophage Migration Inhibitory Factor (MIF) was among the inaugural cytokines to be identified and has emerged as an instrumental element in the genesis and advancement of colonic adenocarcinoma." (PMID 39075485, 2024). "NF‐1 treatment‐induced MIF reduction can reshape the immunosuppressive network and convert a “cold” tumor into a “hot” tumor, thus enabling immunotherapy in BRCA and enhancing the ICB efficacy in colon adenocarcinoma (COAD)." (PMID 39908165, 2025).
colorectal adenoma (3 papers, 2007 to 2025). An adenoma that arises from the colon or rectum. "MIF expression is increased in sporadic human colorectal adenomas." (PMID 17470266, 2007). "Thus, MIF can serve as a clinically relevant drug target in low-stage colorectal adenomas." (PMID 40835826, 2025).
cystic fibrosis (3 papers, 2014 to 2021). Autosomal recessive disorder caused by pathogenic variants in the CFTR gene (cystic fibrosis transmembrane conductance regulator), which encodes a chloride and bicarbonate channel expressed in epithelial cells, and follow the diagnosis criteria. "Genotype frequencies were determined in 189 Cystic Fibrosis and 134 control subjects; key clinical features of patients were recorded and compared among homozygous 5-allele patients and the other MIF genotypes." (PMID 25503271, 2014). "Clinical data of 187 Cystic Fibrosis patients homozygous for the F508del mutation according to the genotype for the MIF gene -CATT repeat at position −794." (PMID 25503271, 2014). "Therefore, only the Homozygous 5-repeat genotype at MIF −794 is associated with milder disease in F508del Cystic Fibrosis patients." (PMID 25503271, 2014). "The 5-CATT allele is associated with lower basal MIF promoter activity in vitro and the homozygous 5-CATT allele is associated with F508del cystic fibrosis." (PMID 27598332, 2016).
diabetic neuropathy (3 papers, 2020 to 2021). A chronic, pathological complication associated with diabetes mellitus, where nerve damages are incurred due to diabetic microvascular injury involving small blood vessels that supply these nerves, resulting in peripheral and/or autonomic nerve dysfunction. "Despite the evidence that glucocorticoids and MIF are associated with neuropathic pain, the role of MIF–glucocorticoid interactions in diabetic neuropathy remains poorly defined." (PMID 32591628, 2020). "There are methodological concerns to conduct further investigation of the upstream pathways and the effect of MIF to better explain the mechanisms associated with the effects of excessive walking on diabetic neuropathy." (PMID 32591628, 2020). "We previously reported that MIF can aggravate diabetic neuropathy by suppressing glyoxalase I and intraepidermal nerve fibers on the footpad skin." (PMID 34445689, 2021). "MIF has been suggested to aggravate diabetic neuropathy by suppressing glyoxalase-I." (PMID 34831154, 2021). "However, further investigation is required in order to better dissect the mechanisms involved in the effects of excessive walking exercise and MIF in diabetic neuropathy." (PMID 32591628, 2020).
dry eye (3 papers, 2009 to 2022). "This induced experimental dry eye and was associated with the sustained elevation of MIF expression within the lacrimal glands." (PMID 21152395, 2010). "The expression of MIF in the lacrimal gland was elevated in a mouse model of keratoconjunctivitis sicca." (PMID 35967518, 2022). "Recently our group reported a high level of MIF expression in the normal murine lacrimal gland and a dynamic change of MIF expression in an experimentally induced murine dry eye model." (PMID 21152395, 2010). "Further studies are underway incorporating both overexpressing MIF transgenic as well as MIF knockout mice in hopes of better understanding the role of this potent inflammatory mediator in our dry eye mouse model." (PMID 19190733, 2009). "In our previous reports using the botulinum toxin B-induced murine dry eye model, TNF-α and IL-1β were increased on both the ocular surface and lacrimal gland, whereas MIF was increased only in the lacrimal gland." (PMID 21152395, 2010). "Although no significant role for MIF on the ocular surface was detected in our dry eye model, the role of MIF in chemical burns could differ profoundly." (PMID 21152395, 2010). "An interesting finding in this study is that MIF was expressed constitutively in corneal and conjunctival epithelia of our mice, and that there was no significant change in the BTX-B-induced dry eye mouse model." (PMID 19190733, 2009).
gestational diabetes (3 papers, 2015 to 2025). Carbohydrate intolerance first diagnosed during pregnancy. "MIF has also been implicated in gestational diabetes, with higher serum MIF in women with gestational diabetes (11.2 ± 0.75 ng/ml) than in healthy pregnant controls (5.31 ± 0.64 ng/ml)." (PMID 26124760, 2015). "Moreover, proof-of-concept studies found that secreted placental proteins (sFLT1/MIF and ANGPT2/MIF ratios) were increased in women prior to diagnosis of gestational diabetes." (PMID 34103657, 2021).
glomerulosclerosis (3 papers, 2015 to 2019). A hardening of the kidney glomerulus caused by scarring of the blood vessels. "The hypothesis is that the G/C substitution at 173 bp of the MIF gene increases the MIF level in serum and could therefore cause a pro-inflammatory response, induce injury to podocytes, and accelerate the progression of glomerulosclerosis." (PMID 29549463, 2019). "The upregulation of the podocyte-expressed MIF induces an injury of podocytes and accelerates the progression of glomerulosclerosis." (PMID 28105926, 2016). "The urinary excretion of MIF before treatment positively correlated with interstitium volume, glomerulosclerosis grade and serum creatinine concentration: ρ = 0.29, P = 0.036; ρ = 0.24, P = 0.038; ρ = 0.31, P = 0.039, respectively." (PMID 26272322, 2015). "The pre-treatment MIF urinary excretion value in PGN positively correlated with interstitium volume, glomerulosclerosis grade and serum creatinine concentration: ρ = 0.28, P = 0.03; ρ = 0.3, P = 0.037; ρ = 0.34, P = 0.026; respectively." (PMID 26272322, 2015).
goiter (3 papers, 2014 to 2021). Enlargement of the thyroid gland usually caused by lack of iodine in the diet, hyperthyroidism, or thyroid nodules. "In Graves' disease (GD), MIF-173G/C plays a dual effect, which is not only a risk factor for the morbidity of goiter but also a protective role in the development of untreated severe goiter." (PMID 32410863, 2020). "The distribution of the MIF polymorphisms among patients with different severities of goiter (grades 0, 1A, 1B, 2, and 3) as well as in healthy controls were analyzed." (PMID 24667663, 2014). "In summary, our findings provide new information pertaining to the role of MIF gene polymorphisms and show that the rs755622 SNP is associated with the severity of goiter in patients with untreated GD in a Taiwanese Chinese population." (PMID 24667663, 2014). "The specific function of MIF that is affected in GD and the mechanism(s) underlying the association of the rs755622 SNP in MIF with goiter in GD need to be addressed in further studies." (PMID 24667663, 2014). "It appears likely that a robust MIF response plays a protective role against development of severe goiter in patients with untreated GD." (PMID 24667663, 2014). "We conclude from our data that genetic variation in the MIF gene may influence the severity of goiter in patients with untreated GD." (PMID 24667663, 2014). "Moreover, the possibility that both cell type-specific and time-course-of-disease-dependent changes in the transcription of MIF might affect its role in the prevention of severe goiter cannot be excluded." (PMID 24667663, 2014).
hemorrhagic fever (3 papers, 2012 to 2019). An infectious disease caused by certain viruses or bacteria that can damage the walls of tiny blood vessels, making them leak, and can hamper the blood's ability to clot and cause severe, life-threatening illness. "Hemorrhagic fever with renal syndrome cases were characterized by a strong expression of MIF, IL-12p40, IL-3, IL-16, CXCL9, CCL27, CXCL1, and HGF." (PMID 28572804, 2017). "MIF can induce vascular leakage during DENV infection, thereby promoting hemorrhagic fever." (PMID 31632367, 2019).
IgA nephropathy (3 papers, 2011 to 2022). "The results of a previous study showed that tubular epithelial MIF expression was significantly upregulated in renal puncture pathological tissue of patients with IgA nephropathy, and hyperplastic mesangial cells also expressed MIF37." (PMID 36329091, 2022). "It has been reported that urinary MIF is increased in patients with IgA nephropathy (IgAN) and correlated with progressive renal injury including glomerular crescent formation." (PMID 35563296, 2022). "In experimental IgA nephropathy, treatment with an anti-MIF monoclonal antibody is also able to suppress renal injury by inhibiting renal TGF-β1 expression." (PMID 35563296, 2022). "MIF produced by T cells from IgAN patients was also reduced after steroid treatment, suggesting the counter-regulation between MIF and glucocorticoids in the pathogenesis of IgA nephropathy." (PMID 35563296, 2022). "This is supported by the findings that MIF-producing T cells are exclusively localized to the area of severe tissue injury, including crescentic GN, IgA nephropathy, focal glomerular and tubulointerstitial lesions, and necrotic vascular inflammation in human renal allograft rejection." (PMID 35563296, 2022). "In experimental IgA nephropathy, treatment with a neutralizing MIF antibody can inhibit IgAN by blocking TGF-β1 expression, suggesting a role of MIF in the pathogenesis of IgAN." (PMID 35563296, 2022).
invasive breast carcinoma (3 papers, 2009 to 2022). A carcinoma that infiltrates the breast parenchyma. "We correlated the expression of MIF with histopathological parameters and patient outcome data, using a tissue microarray of 175 primary invasive breast cancers and 35 normal control tissues." (PMID 19602265, 2009). "The in vitro studies suggested that exogenous MIF derived from the tumour microenvironment promotes proliferation, adhesion, and invasion of CD74+ invasive breast cancer cells." (PMID 19602265, 2009).
joint Disease (3 papers, 2020 to 2022). "Plasma MIF level could serve as a potential biomarker to differentiate OA from other joint diseases such as RA and AS." (PMID 33610191, 2021). "Reduced MIF mRNA and protein expression in OA patients suggested MIF might have a protective role in OA and could serve as a biomarker to differentiate OA from other joint disorders." (PMID 33610191, 2021).
keratitis (3 papers, 2010 to 2024). A corneal disease that is characterized by inflammation of the cornea. "In a different study featuring a Pseudomonas aeruginosa-induced keratitis model, MIF induced corneal epithelial cells to produce proinflammatory cytokines." (PMID 39273646, 2024). "Among these, increased expression of miR-451a in keratitis appeared to correlate with reduced expression of one of its target genes, macrophage migration inhibitory factor (MIF), suggesting potential regulatory functions." (PMID 31533211, 2019). "We found that mice deficient for macrophage migration inhibitory factor (MIF), a key regulator of inflammation, had significantly reduced consequences from acute P. aeruginosa keratitis." (PMID 20361053, 2010). "MIF regulated epithelial cell responses to infection by enhancing synthesis of proinflammatory mediators in response to P. aeruginosa infection and by promoting bacterial invasion of corneal epithelial cells, a correlate of virulence in the keratitis model." (PMID 20361053, 2010).
kidney damage (3 papers, 2010 to 2022). "Cytokines of the TNF family, TNF SNPs, IL-6 serum levels, and IL6 gene SNPs, as well as macrophage inhibiting factor (MIF) and MIF gene variants, might play a role in favoring kidney damage and have been studied." (PMID 35205271, 2022). "Indeed, MIF can be considered a potential biomarker of kidney damage." (PMID 35205271, 2022).
latent infections (3 papers, 2017 to 2024). "Similarly MIF rs12483859 C allele seems be associated with latent infections (p = 0.0077, OR = 1.86, CI95 = [1.18–2.95], BONF = 0.2157)." (PMID 28827791, 2017). "On the other hand, upregulation of MIF expression after latent infection might be employed by MDV to induce lymphoma occurrence." (PMID 38879650, 2024). "On the one hand, decreased expression of MIF during early and latent infection enhances macrophage migration, which might be a potential mechanism by which MDV increases virus transport and spread." (PMID 38879650, 2024). "Our data show that the frequency of the G minor allele of MIF rs36086171 was higher in cases than in controls (uncorrected p = 0.0239, OR = 1.65, CI95 = [1.07–2.53]) and MIF rs12483859 C allele in latent infections than in controls (uncorrected p = 0.0077, OR = 1.86, CI95 = [1.18–2.95])." (PMID 28827791, 2017). "There were suggestive associations at three loci in IL6 and TNFA in the comparison between active cases and controls, one SNP in each of APOL1, MIF and IL6 in the comparison between latent infections and active cases and seven SNP in IL4, HLA-G and TNFA between latent infections and controls." (PMID 29059176, 2017).
medulloblastoma (3 papers, 2011 to 2025). A malignant, invasive embryonal neoplasm arising from the cerebellum. "To further confirm in vivo that MIF was necessary for triggering RANTES production from endothelial cells, we generated MIF-knock down (KD) Daoy medulloblastoma cells using a retroviral vector encoding a MIF-specific shRNA." (PMID 21647415, 2011). "Medulloblastoma cells constitutively release the chemokine MIF which itself cannot recruit T lymphocytes, but triggers the release of a second chemokine, RANTES, from endothelial cells in the tumor stroma." (PMID 21647415, 2011). "This MIF-mediated mechanism may represent one method for recruiting immunosuppressive leukocytes to the medulloblastoma TME." (PMID 39233830, 2024). "Daoy medulloblastoma cells had a distinct chemokine signature, producing MCP-1; Gro-α; MIF; IL-8; Serpin E1; and IL-6." (PMID 21647415, 2011). "Our chemokine array analysis had revealed that all 7 primary medulloblastomas and Daoy secreted MIF, and that neither secreted RANTES." (PMID 21647415, 2011).
meningioma (3 papers, 2013 to 2024). A generally slow growing tumor attached to the dura mater. "We have identified a common mechanism in different pathological subtypes (including atypical, transitional, fibrous, and clear cell) of meningiomas, namely the ubiquitous presence of MIF and CD74-positive macrophage interactions." (PMID 37880655, 2023). "Except for meningiomas, MIF exhibits significantly elevated expression across various cancer types, indicating its potential as a diagnostic biomarker for tumor invasion and recurrence." (PMID 37880655, 2023). "Thus, loss of MIF in meningiomas with isolated monosomy 22/del(22q) may also play an important role in determining the more indolent behavior and the good prognosis of this subgroup of meningioma patients." (PMID 24098347, 2013). "Despite this, it should be noted that the most significant immune response-associated gene coded in chromosome 22, which was lost in this cytogenetic subgroup of meningiomas, is the MIF gene." (PMID 24098347, 2013). "We propose that blocking CD74-positive macrophages from receiving MIF signals and inhibiting their progression to a pro-tumorigenic state may be a key therapeutic strategy for treating different types of meningiomas." (PMID 37880655, 2023). "Immunofluorescence staining results revealed the presence of MIF (green fluorescence) and CD74 (red fluorescence) in atypical, transitional, fibrous, clear cell, and endothelial subtypes of meningiomas." (PMID 37880655, 2023). "In order to ensure the robustness of the broad expression of MIF and CD74 observed within meningiomas, a subsequent investigation was conducted involving an additional cohort of ten meningioma cases." (PMID 37880655, 2023).
metabolic dysfunction-associated steatohepatitis (3 papers, 2021 to 2025). Metabolic dysfunction-associated steatohepatitis (MASH, formerly known as nonalcoholic steatohepatitis or NASH) is a type of fatty liver disease. "However, other research suggests that MIF serves as a defense mechanism, decreasing hepatic inflammatory cells and pro-inflammatory cytokines in nonalcoholic steatohepatitis." (PMID 36160453, 2022).
myelitis (3 papers, 2018 to 2023). An inflammatory process affecting the spinal cord. "In contrast, the appearance of myelitis could lead to a pronounced inflammation, and in turn, yield higher concentrations of MIF in the CSF due to spinal microglia activation." (PMID 30475854, 2018).
neonatal respiratory distress syndrome (3 papers, 2013 to 2021). "We have recently reported that loss of macrophage migration inhibitory factor (MIF) in the mouse leads to impaired lung maturation, akin to a respiratory distress syndrome (RDS) in premature newborns, and increased mortality." (PMID 23637753, 2013). "Macrophage migration inhibitory factor promotes lung development and protects preterm mice from neonatal respiratory distress syndrome and hyperoxia-induced lung injury." (PMID 28179905, 2017).
optic neuritis (3 papers, 2014 to 2021). Optic neuritis is inflammation of the optic nerve, the nerve that carries the visual signal from the eye to the brain.The conditionmay cause sudden, reduced vision in the affected eye(s). "In males, there may be some possible MIF-dependent effects that might include protection from neuronal damage as we have observed in the EAE, optic neuritis, and macular degeneration models." (PMID 24838614, 2014). "In conclusion, MIF might not suitable for distinguishing GC responders from non-responders in optic neuritis." (PMID 30475854, 2018).
oral cancer (3 papers, 2015 to 2024). "The protein expression levels of endogenous HMGA2 and MIF and the effects of their siRNA-mediated silencing in two oral cancer cell lines (SCC4 and SCC25) were determined by Western blotting using anti-HMGA2 and anti-MIF antibodies." (PMID 26138061, 2015).
periodontal disease (3 papers, 2019 to 2025). "And reducing MIF levels was reported to protect against bone loss in OP models of ovariectomy and periodontal disease." (PMID 41404455, 2025). "The high levels of MIF in GCF and saliva could be attributed to the characterized microbial change (from Gram-positive to Gram-negative bacterial strains) during the transition from health to periodontal disease." (PMID 30868074, 2019).